KTN1 (kinectin 1)
Description:
Receptor for kinesin thus involved in kinesin-driven vesicle motility. Accumulates in integrin-based adhesion complexes (IAC) upon integrin aggregation by fibronectin.
Synonyms: CG1; KIAA0004; KNT; MU-RMS-40.19
Tractability: Antibody: its Gene Ontology location is reachable by antibodies, with high confidence; UniProt predicts a signal peptide or a membrane-spanning region. PROTAC: ubiquitination databases record sites on it; its protein half-life has been measured.
Gene: Protein-coding gene on chromosome 14 (55,559,072 to 55,701,526, forward strand). Ensembl gene ENSG00000126777.
Subcellular location: Endoplasmic reticulum membrane
Subcellular location (Human Protein Atlas): Endoplasmic reticulum
Pathways (Reactome):
Signal Transduction: CDC42 GTPase cycle; RAC1 GTPase cycle; RHO GTPases activate KTN1; RHOA GTPase cycle; RHOG GTPase cycle; RND2 GTPase cycle; RND3 GTPase cycle
Metabolism of proteins: Post-translational protein phosphorylation; Regulation of Insulin-like Growth Factor (IGF) transport and uptake by Insulin-like Growth Factor Binding Proteins (IGFBPs)
Gene Ontology:
Molecular function: cadherin binding; protein binding; RNA binding; kinesin binding
Biological process: microtubule-based movement; protein transport
Cellular component: endoplasmic reticulum; membrane; endoplasmic reticulum lumen; endoplasmic reticulum membrane; plasma membrane
Genetic constraint (gnomAD): Loss-of-function variants: 29 observed, 51.46 expected, observed/expected ratio (o/e) 0.56, 90% interval 0.42 to 0.77. The upper end of that interval is the gene's LOEUF score, 0.77, which puts it in group 3 of 6, group 1 being the genes least tolerant of losing a copy. Missense variants: 474 observed, 468.79 expected, observed/expected ratio (o/e) 1.01, 90% interval 0.94 to 1.09. Synonymous variants: 177 observed, 167.52 expected, observed/expected ratio (o/e) 1.06, 90% interval 0.93 to 1.2.
Homologues: Orthologues: chimpanzee KTN1 (99% identical), macaque KTN1 (99% identical), pig KTN1 (93% identical), rabbit KTN1 (89% identical), dog KTN1 (89% identical), mouse Ktn1 (82% identical), rat Ktn1 (81% identical), guinea pig KTN1 (66% identical), tropical clawed frog ktn1 (58% identical), zebrafish ktn1 (39% identical).